MIR6715A (microRNA 6715a)
Synonyms: hsa-mir-6715a
Gene: MicroRNA gene on chromosome 10 (112,299,612 to 112,299,690, forward strand). Ensembl gene ENSG00000276857.
Homologues: Orthologues: chimpanzee MIR6715A (100% identical).